ENSG00000270103 (RNA, U11 small nuclear)
Gene: Long non-coding RNA gene on chromosome 1 (28,648,600 to 28,648,730, forward strand). Ensembl gene ENSG00000270103.
Gene Ontology:
Molecular function: pre-mRNA 5'-splice site binding
Biological process: mRNA 5'-splice site recognition
Cellular component: U11 snRNP